JAK1 (Janus kinase 1)
Diseases named in the same sentence as JAK1 in open-access papers (continued):
Sharing a sentence is not in itself a finding about the gene and the disease.
venous thromboembolism (1 paper, 2023). Occlusion of the lumen of a vein by a thrombus that has migrated from a distal site via the blood stream. "Even prior to the ORAL Surveillance, concerning safety signals appeared during the trials of BARI regarding increased risk of venous thromboembolism (VTE) suggesting a possible class effect of JAK inhibitors, rather than a risk associated solely with TOFA and strong JAK1/JAK3 inhibition." (PMID 37892827, 2023).
VEXAS syndrome (1 paper, 2024). An adult-onset inflammatory disease that affects only males and is caused by somatic, not germline, mutations. "Due to the limited data available on treatment options in VEXAS syndrome, an off-label use of the JAK1/2 inhibitor ruxolitinib was initiated at 20 mg twice daily, and glucocorticoids were discontinued." (PMID 38398362, 2024). "In particular, the JAK1/2 inhibitor ruxolitinib appears to be a suitable candidate for reducing the concurrent need for glucocorticoids in VEXAS syndrome patients, whether or not they have myeloid neoplasia." (PMID 38398362, 2024).
tumor (456 papers, 2002 to 2026). "High‐frequency JAK1 mutations, such as S729C, S703I, and V617F, contribute to tumor progression by acting as either oncogenic drivers or tumor suppressors." (PMID 40344393, 2025). "The activation of the JAK1/STAT6 pathway was found to be associated with tumor progression and M2 polarization." (PMID 40604704, 2025). "We investigated the prevalence of those mutations before ICB by collating data from The Cancer Genome Atlas (TCGA) for pre-treatment tumours which harboured mutations in the IFNγ receptor subunits (IFNGR1/2) or downstream signalling molecules (JAK1/2, STAT1)." (PMID 39746898, 2025). "Collectively, our results suggest that inhibition of JAK1/STAT3 pathway by p27 is associated with its tumour suppressive effect in lung carcinogenesis." (PMID 39099000, 2024). "Whole-exome sequencing of their tumor tissues obtained at baseline and after disease progression revealed over 90% truncating dysfunctional mutations in both JAK1 (Q503* nonsense mutation) and JAK2 (F547 splice-site mutation)." (PMID 38785789, 2024). "JAK1/2-inactivating mutations have been shown to increase tumor resistance to Pembrolizumab, an anti-PD-1 therapy, by disabling the IFN-γ responsive pathway." (PMID 39273605, 2024). "Again, ovalbumin-specific OT-II TCRtg CD4+ T cells were able to eradicate ovalbumin-expressing MHC-deficient HCmel12 Jak1-KO tumours, whereas ovalbumin-specific OT-I TCRtg CD8+ T cells were ineffective." (PMID 37316667, 2023). "The activity across many immune cells led to AC484 efficacy in settings in which T cell immunity is insufficient to control tumour growth, such as in JAK1-deficient or MHC class I-deficient tumours, and the surveillance of metastasis." (PMID 37794185, 2023). "That’s caused by an important mechanism of immune escape involving tumor cells’ defects in the IFNγ receptor kinases JAK1 and JAK2 and the signal transducer and activator of transcription (STAT) molecules." (PMID 37100920, 2023). "The increased immune cell infiltrate was less pronounced in MHC-deficient HCmel12 Jak1-KO tumours when compared to HCmel12 CRISPR-ctrl tumours, in line with our observation in patient samples." (PMID 37316667, 2023). "Although tumor cells were still recognized by T cells, their JAK1/2 mutation rendered them insensitive to the anti-proliferative effects of IFN-γ and they lacked IFN-γ-induced PD-L1 and MHC class I surface expression." (PMID 37637050, 2023). "We functionally validate variants of uncertain significance in primary tumor organoids, where engineering missense mutations in JAK1 enhanced or reduced sensitivity to autologous tumor-reactive T cells." (PMID 36669486, 2023). "We confirmed the fundamental difference in the spatial distribution and migratory behaviour of CD4+ and CD8+ T cells in tumour tissues using amelanotic (Tyr-KO) MHC-deficient HCmel12 Jak1-KO tumours that express tagBFP-Ova." (PMID 37316667, 2023). "Preclinical studies have shown that defects in IFNGR1 (IFN-γ receptors) and JAK1/2 genes cause tumor cells to be unresponsive to IFN- γ, which allows tumor cells to grow in the presence of IFN- γ." (PMID 35740594, 2022). "A total of 167 JAK1 mutations occurred in approximately 30.6% (167/546) of the tumor specimens, including 80 truncating, 76 missense, and 11 splice site mutations." (PMID 36376931, 2022). "The data suggested that cytokine receptor signaling is required for the survival of tumor cells, even in the presence of JAK1/STAT3 mutations." (PMID 35406421, 2022). "HRAS and JAK1 mutations are less frequent in tumours with high NCS and KRAS mutations are under-represented in samples with high SCS." (PMID 35326573, 2022). "The JAK1/2 mutations in tumor cells cause the survival of the tumor cells by resisting the antiproliferative effects of IFN-γ." (PMID 34829916, 2021).
tumor (continued). "Not only immunogenic neoantigens, but also mutations in immunologically relevant genes, can affect the ability of T cells to identify and kill tumor cell, for example; mutations in JAK1, JAK2, B2M, and STK11genes." (PMID 34319027, 2021). "Not only immunogenic neoantigens affect the ability of T cells to identify and kill tumor cell, but mutations in immunologically relevant genes can also do, for example; mutations in JAK1, JAK2, B2M, and STK11genes." (PMID 34319027, 2021). "In the further exploratory analysis, PTPRD/PTPRT mutation was significantly associated with increased tumor mutation burden and higher mRNA expression of JAK1 and STAT1." (PMID 34123798, 2021). "This was an unexpected finding since the Flp recombinase was able to delete the frt-flanked neomycin cassette in the conditional Jak1 knockout alleles in addition to activating the FSF-KrasG12D that led to tumor formation (upper)." (PMID 34675248, 2021). "Further, Jak1 deficiency impaired NK cell anti-tumor surveillance and activity, indicating that Jak1 is necessary for optimal innate immune function." (PMID 35056105, 2021). "In line with our circulating biomarker data, we found that a high level of IL10RA or JAK1 gene expression in tumor tissue was significantly associated with shorter survival after LR in the HCC patients from the TCGA dataset." (PMID 32443546, 2020). "Janus kinase 1(JAK1) is a critical effector of pro-inflammatory cytokine signaling and immune function and abnormal JAK1 activity has been linked to immunological and neoplastic diseases." (PMID 32640596, 2020). "Frameshift JAK1 mutations involved the hotspot position K860/P861 (deletions in 5 tumors and insertion in 1 tumor) and the hotspot position P430/L431 (insertions in 2 tumors)." (PMID 32494760, 2020). "In patients receiving immunotherapy, tumor cells can downregulate or alter IFN-γ signaling pathways such as loss-of-function alleles of genes encoding for JAK1/2 and changes in STAT1 to escape the influence of IFN-γ, resulting in resistance." (PMID 32850400, 2020). "To this end, we mutated IFNγR2 and Jak1 in B16F10 tumor cells using the same single-cell method and confirmed successful disruption of IFN-γ signaling." (PMID 32001684, 2020). "The association between JAK1 and tumor immune cell infiltration was investigated using the TIMER and CIBERSORT databases." (PMID 33323549, 2020). "Cytokine signaling through GP130-IL6ST and JAK1 stimulates actomyosin-mediated contractility in cancer cells and in the tumor-associated stroma." (PMID 32546182, 2020). "Somatic mutations predicted to cause loss of JAK1 function are associated with reduced expression of IFN-associated genes in different tumor types." (PMID 31552026, 2019). "Histological examination of the invasive urothelial carcinoma found in the JAK1-deficient patient revealed a heterogeneous tumor with distinct central and invasive regions." (PMID 31552026, 2019). "The biological relevance of patient-derived T-cells against neoantigens from known cancer-associated genes, NUP214 and JAK1, were confirmed by the demonstration of autologous tumor recognitions." (PMID 31221207, 2019). "TNF-α, granzyme B, and perforin were all downregulated in cells lacking JAK1; this was rescued by the re-expression of codon-optimized JAK1, implying that JAK1 deficiency prevents killing by tumor-specific T-cells." (PMID 30837996, 2019). "Whole exome sequencing of tumours from patients that developed resistance following initial clinical response to PD-1 blockade revealed mutations in Janus kinases 1 and 2 (JAK1/JAK2)." (PMID 29319049, 2018). "In contrast, deletion of JAK1 in mature NK cells leads to NK cell deficiency and loss of one allele of Jak1 is sufficient to impair tumor growth control." (PMID 30671064, 2018). "Using CRISPR, we generated B16 tumor cell lines deficient in type I (Ifnar1-KO) or type II (Jak2-KO) interferon signaling, or both (Jak1-KO)." (PMID 30400822, 2018).
tumor (continued). "Deletion of one allele of Jak1 is also sufficient to significantly impair tumor surveillance based on decreased numbers of NK cells combined with a diminished functionality of the remaining NK cells." (PMID 30671064, 2018). "MSI-H tumors exhibit increased mutation rates; therefore, we also tested the association of JAK1 frameshifts with tumor mutational burden (TMB)." (PMID 29121062, 2017). "We concluded that multiple mutations in JAK1 and reduced expression were indicative of loss of function mutations commonly found in tumor suppressor genes." (PMID 29121062, 2017). "In total, we conclude that JAK1 frameshift mutations are a potential pan-cancer adaptation to anti-tumor immunity and that these alterations likely result in a lack of antigen presentation and resistance to interferons." (PMID 29121062, 2017). "The oncogene JAK1 contained a high impact mutation within aggressive PET-10 tumor, while high impact mutations were identified in CARD11, NF2 and ORC1 within aggressive PET-20, and in DPY19L2 and SNRPC within non-aggressive PET-24." (PMID 29100308, 2017). "Further, the tumor growth of HCC PDX model bearing JAK1S703I mutation was sensitive to treatment of a JAK1/2 inhibitor, ruxolitinib." (PMID 26701727, 2016). "Two of these three JAK1 mutant MSS cases showed focal loss of MLH1 protein expression in part of the tumor as a result of MLH1 promoter hypermethylation." (PMID 27213585, 2016). "In this regard, we demonstrated that pharmacologic antagonism of JAK in primary SS samples harbouring JAK1 mutations led to significant inhibition of tumour cell proliferation." (PMID 26415585, 2015). "Our results suggest that high local production of complement component 5 (C5) and janus kinase 1 (JAK1) at tumour site associates with better survival of ESFT patients, whereas locally produced interleukin 8 (IL8) is detrimental." (PMID 22084725, 2011). "Primary resistance occurs when tumor cells are intrinsically incapable of responding to the immune checkpoint blockade due to defects in antigen presentation, such as the loss of β2-microglobulin or mutations in JAK1/2." (PMID 40565559, 2025). "Additionally, Jak1 loss significantly reversed tumor growth impairment mediated by the combination of TAK-243 and anti–PD-1." (PMID 39540840, 2025). "Based on these data, we inferred that Con-A + SB-treated cells had significantly lower expression levels of proteins linked to tumor formation, such as JAK1, STAT3, PCNA, cyclin D1, along with evidence of G2/M phase arrest, as indicated by the downregulation of Cyclin B and Cdk1." (PMID 40350446, 2025). "Interestingly, we observed the presence of JAK1 mutations in five patients (5/15, 33%), which is comparable to the frequency of JAK1 mutations among dMMR/MSI-H tumours in The Cancer Genome Atlas (TCGA) dataset (91/400, 23%)." (PMID 36870947, 2023). "However, we have previously shown that immunity in Jak1-deficient tumours, which express low levels of MHC class I molecules, depends on NK cells." (PMID 37794185, 2023). "Mechanisms of resistance likely include specific tumor-cell genetics (loss-of-function mutations in JAK1/2), and differing expression levels of tumor-cell surface proteins (e.g., MHC I expression, alternate ICIs, and epigenetic T-cell changes limiting effector function and memory)." (PMID 35453572, 2022). "Therefore, mutations and deletions of proteins associated with this pathway on tumor cells, such as JAK1 and JAK2, STAT1, IRF1, and other IFN receptor chains, can lead to drug resistance to immunocheckpoint inhibitors." (PMID 36185620, 2022). "The tumor develops escape mutations: Mutations in JAK1/JAK2 may result in tumor escaping the antiproliferative effect of INF-γ." (PMID 35198442, 2022).
tumor (continued). "Some mechanisms that lead tumor cells to escape immunotherapy are the downregulation or mutating molecules involved in the IFN-γ signalling pathway by tumor cells, like the loss-of-function of genes encoding for JAK1/2 and changes in STAT1 to escape the influence of IFN-γ." (PMID 34829916, 2021). "Whether JAK1 mutations can induce changes in the tumor immune microenvironment in underweight patients requires further study." (PMID 33868999, 2021). "Furthermore, JAK1/JAK2-deficient tumor cell populations can silence HLA class I antigen presentation, which hinders T-cell recognition." (PMID 32111080, 2020). "We confirmed the loss of IFN-γ signaling in IFNγR2- and Jak1-mutant MC38 tumor cell clones." (PMID 32001684, 2020). "Loss of IFNγ responsiveness in tumor cells may result from inactivating mutations in JAK1/2 disrupting INFγ signaling, leading to tumor immune escape and disease progression." (PMID 32992658, 2020). "Our observations suggest that although cancer cells may evade immunological attack by mutating genes such as JAK1, de novo T-cell responses against such mutations might be exploited to inhibit tumor growth in cancer patients." (PMID 31221207, 2019). "Since loss of JAK1 induced tumor resistance to IFNs in vitro, we examined whether it altered the therapeutic effects of IFN-α in vivo by treating mice bearing B16/OVA or B16/OVA-JAK1−/− cell-derived tumors with IFN-α4." (PMID 30837996, 2019). "Moreover, tumours positive for JAK1, PD1 and PDL1 were associated to a favorable prognosis as compared to those negative ones." (PMID 30670049, 2019). "Importantly, the impact of systemic JAK1/2 inhibition with a small molecule inhibitor (e.g., ruxolitinib) almost certainly differs from tumour-specific loss of functional JAK1 and/or JAK2 signalling." (PMID 29319049, 2018). "The effect of the drug on modulation of STAT3 phosphorylation may also be linked with the inhibition of upstream proteins such as JAK1/2 and c-Src, as we noticed that it can substantially reduce the constitutive activation of these kinases in tumor cells." (PMID 30413072, 2018). "However, some tumor samples with JAK1 frameshift mutations in the TCGA dataset exhibited high expression of IFNγ response genes." (PMID 29121062, 2017). "Therefore, we analyzed the mutant allele frequency of JAK1 early terminating mutations and JAK1 ploidy to determine the cancer cell fraction in tumor samples." (PMID 29121062, 2017). "However, in case of JAK1/2 deficiency IFNγ-induced restoration of antigen presentation in tumour cells is abrogated." (PMID 28561041, 2017). "JAK1/2-deficient tumour cells emerged in disease stage IV metastases under/after immunotherapy." (PMID 28561041, 2017). "For example, we found that CXCL12 and JAK1 are both more highly expressed in low risk tumours." (PMID 27469239, 2016). "Impaired upregulation of HLA class I expression interferes with tumor lysis by cytotoxic T-cells, and therefore JAK1 mutations may facilitate an immune escape." (PMID 27213585, 2016). "Furthermore, we validated clinically observed JAK1 missense variants in CRC-9 tumor organoids using individual gRNAs, as shown by altered sensitivity to IFN-γ in three-dimensional growth assays, with LOF missense mutations at JAK1 residues 108, 590, and 775 conferring resistance." (PMID 36669486, 2023). "Indeed, the defective TAP1 and LMP2 expression in these tumors is associated with a G871E mutation in the ATP-binding region of the JAK1 kinase domain, thereby affecting JAK1 kinase activity, but neither JAK1 expression nor its degradation allow the tumor cells to evade anti-tumor specific immunity." (PMID 37047709, 2023). "In addition, loss of YTHDF1 mediated the overexpression of IFNGR1 and JAK1/2-STAT1 pathway in tumor cells, which might contribute to restored sensitivity to antitumor immune response." (PMID 35193930, 2022). "Thus, JAK1 deficiency impairs the activation of tumor-specific T-cell responses." (PMID 30837996, 2019).